POLR3C (RNA polymerase III subunit C)
Description:
DNA-dependent RNA polymerase catalyzes the transcription of DNA into RNA using the four ribonucleoside triphosphates as substrates. Specific peripheric component of RNA polymerase III (Pol III) which synthesizes small non-coding RNAs including 5S rRNA, snRNAs, tRNAs and miRNAs from at least 500 distinct genomic loci. Part of POLR3C/RPC3-POLR3F/RPC6-POLR3G/RPC7 heterotrimer, coordinates the dynamics of Pol III stalk and clamp modules during the transition from apo to elongation state. Pol III plays a key role in sensing and limiting infection by intracellular bacteria and DNA viruses. Acts as a nuclear and cytosolic DNA sensor involved in innate immune response. Can sense non-self dsDNA that serves as template for transcription into dsRNA. The non-self RNA polymerase III transcripts, such as Epstein-Barr virus-encoded RNAs (EBERs) induce type I interferon and NF-kappa-B through the RIG-I pathway. Preferentially binds single-stranded DNA (ssDNA) in a sequence-independent manner.
Synonyms: RPC62; RPC3; C82
Tractability: Small molecule: a structure with a bound ligand is known. PROTAC: ubiquitination databases record sites on it; its protein half-life has been measured.
Gene: Protein-coding gene on chromosome 1 (145,823,959 to 145,844,721, forward strand). Ensembl gene ENSG00000186141.
Subcellular location: Nucleus
Subcellular location (Human Protein Atlas): Nucleoplasm
Pathways (Reactome):
Gene expression (Transcription): RNA Polymerase III Abortive And Retractive Initiation; RNA Polymerase III Chain Elongation; RNA Polymerase III Transcription Initiation From Type 1 Promoter; RNA Polymerase III Transcription Initiation From Type 2 Promoter; RNA Polymerase III Transcription Initiation From Type 3 Promoter; RNA Polymerase III Transcription Termination
Immune System: Cytosolic sensors of pathogen-associated DNA
Gene Ontology:
Molecular function: protein binding; single-stranded DNA binding; DNA-directed RNA polymerase activity; DNA binding
Biological process: positive regulation of innate immune response; positive regulation of interferon-beta production; termination of RNA polymerase III transcription; transcription by RNA polymerase III; transcription initiation at RNA polymerase III promoter; regulation of transcription by RNA polymerase III; DNA-templated transcription
Cellular component: nucleoplasm; nucleus; RNA polymerase III complex; cytosol
Genetic constraint (gnomAD): Loss-of-function variants: 15 observed, 21.83 expected, observed/expected ratio (o/e) 0.69, 90% interval 0.46 to 1.06. The upper end of that interval is the gene's LOEUF score, 1.06, which puts it in group 4 of 6, group 1 being the genes least tolerant of losing a copy. Missense variants: 242 observed, 279.64 expected, observed/expected ratio (o/e) 0.87, 90% interval 0.78 to 0.96. Synonymous variants: 112 observed, 99.12 expected, observed/expected ratio (o/e) 1.13, 90% interval 0.97 to 1.32.
Homologues: Orthologues: chimpanzee POLR3C (100% identical), macaque POLR3C (98% identical), pig POLR3C (96% identical), rabbit POLR3C (96% identical), mouse Polr3c (93% identical), rat Polr3c (93% identical), guinea pig POLR3C (93% identical), dog POLR3C (92% identical), tropical clawed frog nudt17 (76% identical), zebrafish polr3c (65% identical), Drosophila melanogaster Polr3C (30% identical), Caenorhabditis elegans let-611 (23% identical).
Diseases named in the same sentence as POLR3C in open-access papers:
POLR3C is named in the same sentence as 18 diseases in open-access papers, as found by Europe PMC text mining. Sharing a sentence is not in itself a finding about the gene and the disease. The quoted sentences say what the papers report.
breast carcinoma (2 papers, 2020 to 2024). "—Downregulation of three (POLR3A, POLR3C, POLR3GL) catalytic components of RNA polymerase III, which synthesize small RNAs and were suggested as potential targets for breast cancer." (PMID 33302383, 2020).
schizophrenia (2 papers, 2013 to 2018). A major psychotic disorder characterized by abnormalities in the perception or expression of reality. "Copy number variants in the human ortholog of the Polr3c gene have been reported in schizophrenic patients, and Polr3c was proposed as a schizophrenia candidate gene relative to a number of metabolites altered in plasma samples from schizophrenic patients." (PMID 29768498, 2018).
bipolar disorder (1 paper, 2018). A disorder of the brain that causes unusual shifts in mood, energy, activity levels and the ability to carry out day-to-day tasks. "The variants are in the Npas2, Cp, Polr3c, Smarca4, Trpv1, and Slc5a7 genes, and many of these genes’ products are in pathways implicated in human bipolar disorders." (PMID 29768498, 2018).
chickenpox (1 paper, 2022). A contagious childhood disorder caused by the varicella zoster virus. "Heterozygous mutations in genes encoding four Pol III subunits, POLR3A/RPC1, POLR3C/RPC3, POLR3E/RPC5, POLR3F/RPC6, compromise this immune response to Varicella Zoster Virus (chickenpox)." (PMID 35813003, 2022).
encephalitis (1 paper, 2021). An acute inflammatory process affecting the brain parenchyma. "Mutations in the POLR3A, POLR3C, POLR3E and POLR3F subunits are associated with susceptibility to varicella zoster virus-induced encephalitis and pneumonitis." (PMID 34395528, 2021).
primary immunodeficiencies (1 paper, 2021). "However, no errors in innate immune genes or other rare primary immunodeficiencies were discovered; specifically, there were no errors in RNA polymerase III genes (POLR3A and POLR3C)." (PMID 34835092, 2021).
systemic sclerosis (1 paper, 2025). A chronic disorder, possibly autoimmune, marked by excessive production of collagen which results in hardening and thickening of body tissues. "Anti-RNA polymerase III subunit C (RPC1) autoantibodies are commonly found in patients with systemic sclerosis (SSc)." (PMID 40416967, 2025).
virus infection (1 paper, 2018). "There is evidence that POLR3C (RNA polymerase III subunit C) was be associated with virus infection." (PMID 30243023, 2018).
tumor (4 papers, 2014 to 2023). "Analysis of CHD1L correlated proteins in the tumor tissue revealed that POLR3C, PRKAB2, SETDB1, GPATCH4, and MSTO1 were the top five ones." (PMID 37033447, 2023). "Analysis of RACGAP1 correlated proteins in the tumor tissue revealed that POLR3C, PRKAB2, SETDB1, GPATCH4, and MSTO1 were the top five." (PMID 36430577, 2022).
POLR3C also shares sentences with these, for which no sentence is quoted: bacterial infection (1 paper); basal cell carcinoma (1); cancer of female genital organs (1); cancer of male genital organs (1); hepatocellular carcinoma (1); neuropathy (1); pneumonitis (1); skin cancer (1); varicella zoster virus infections (1).